BRAF (B-Raf proto-oncogene, serine/threonine kinase)
Diseases named in the same sentence as BRAF in open-access papers (continued):
Sharing a sentence is not in itself a finding about the gene and the disease.
tumor (continued). "In addition, increased tumor T‐cell infiltration in BRAF inhibitor‐treated patients disappears in biopsies collected after 15 days from treatment initiation, suggesting that tumor cells develop a ‘counter‐strike’ strategy to delete T cells." (PMID 32330348, 2020). "Several mechanisms account for the reduction in tumour response to BRAF inhibitor therapy." (PMID 32645969, 2020). "In addition, BRAF-WT patients achieved a higher rate of median early tumor shrinkage (ETS) at time of first radiological reassessment in comparison with BRAF-MT patients [85.2% (95% CI 72.9–93.4%) vs. 33.3% (95% CI 9.9–65.1%); p = 0.001]." (PMID 32449003, 2020). "Soon, a re-challenge strategy using anti-EGFR therapy may be active in patients with RAS and BRAF wild-type tumours, who have acquired resistance to first-line cetuximab-based therapies." (PMID 32605298, 2020). "For patients with RAS or BRAF mutation, regardless of tumor location, FOLFOXIRI ± bevacizumab is recommended." (PMID 32161617, 2020). "Among all 70 non-BRAF V600E-mutated cases, only one case with ALK fusion (confirmed by positive ALK[D5F3] IHC) provided a false positive result with positive cytoplasmic and nuclear staining in 80% of tumor cells." (PMID 31234388, 2019). "Tumor heterogeneity could result in missed RAS‐ and BRAF‐mutated subclones, present under the detection limit of the assay or not present in the evaluated part of the tumors." (PMID 31350822, 2019). "Tumor tissues screening by PCR PNA SNaPshot or Sequenom mass spectrometry-based assay of these later patients did not reveal BRAF non-V600E mutations." (PMID 31319569, 2019). "Interestingly, the top predictions from genomic data across tumor types were all MEK inhibitors (PD0325901, selumetinib, and trametinib), which were associated with BRAF and KRAS/NRAS mutations." (PMID 31253656, 2019). "Right-sided tumours have been associated with the presence of KRAS and BRAF mutations." (PMID 30843120, 2019). "No mutation in the 13 other genes covered by the TruSight Tumor 15 gene panel was observed in any case, except for the BRAF mutation detected in the single primary tumor being KRAS-negative." (PMID 30611220, 2019). "Factors found to be significantly associated with worse OS were age 15–39 years (p = 0.002), right-sided tumour (p < 0.001), poor differentiation (p < 0.001), signet ring cell feature (p < 0.001), KRAS mutation (p = 0.013), BRAF mutation (p < 0.001) and pMMR (p = 0.016)." (PMID 31406299, 2019). "Of the four patients with the BRAF mutation in plasma, but not in the paired tumor tissue, two were positive for a BRAF non-V600E mutation (one p.Asp594His and one p.Lys601Glu mutation)." (PMID 31319569, 2019). "Whereas the p.BRAF-V600E mutation was retained, the recurrent tumour showed an additional p.NF1-E1571* nonsense mutation (not shown)." (PMID 31747973, 2019). "In these unusual cases, it is unclear whether BRAF and KRAS mutations co-exist within the same tumor cells, implying tumor progression, versus a “collision” event, involving separate tumor populations arising from different cells of origin." (PMID 31839880, 2019). "We observed statistically significant differences between BRAF-mutated and -wildtype tumors and tumor purity (P = 0.036), but no statistically significant results for the leukocyte fraction (P = 0.057)." (PMID 31747929, 2019). "There were 6 tumors with coexisting mutations of the same gene (1 with 2 BRAF, 2 with 2 NRAS, 1 with 2 PIK3CA, 1 with 2 KIT, and 1 with 3 KIT mutations), and 26 tumors with coexisting mutations of different genes, including a tumor with 2 NRAS and one PIK3CA mutation." (PMID 31277584, 2019).
tumor (continued). "Forty one patients with baseline LB sample presented archival tumor tissue mutated for KRAS, NRAS, or BRAF (68.3%), and 38/41 (92.6%) demonstrated concordant status for the expected patient specific mutations, as supported by more than one mutational event out of two replicates." (PMID 31355139, 2019). "Radiographically, the majority of BRAF V600E CNS-JXG neoplasms had multifocal CNS disease, often with contrast enhancement and a subset were noted to have background white matter changes, suggestive of neurodegeneration, which is also a feature shared in cases of CNS-ECD and CNS-LCH." (PMID 31685033, 2019). "No BRAF or KRAS mutation was detected in cfDNA from patients with wild‐type tumor tissue, resulting in 100% assay specificity among all four cancer stages." (PMID 31134762, 2019). "Interestingly, patient 8 had 1 tumor sample harboring only cell cycle deregulation through RB1 deletion confirming its major role in resistance to BRAF inhibitors." (PMID 30899440, 2019). "However, one tumor harbored a disease-associated variant in HRAS, and a BRAF p.(V600E) disease-associated variant was detected in another." (PMID 31046843, 2019). "Therefore, we suggest that under certain conditions, such as small tissue samples with a limited number of tumor cells, the BRAF V600E (VE1) IHC test should be more carefully evaluated and rebiopsy for molecular testing should be considered." (PMID 31234388, 2019). "Since concomitant KRAS and BRAF tumor mutations are considered mutually exclusive we wanted to confirm that the CRC cases carrying KRAS mutation show negative BRAF V600E staining by IHC with anti-BRAF V600E (VE1) antibody." (PMID 29127628, 2019). "Moreover, expansion and activation of CD103+ cDC1 progenitors at the tumor site by simultaneously administering FLT3L and poly I:C enhances tumor responses to BRAF inhibitors and PD-L1 blockade." (PMID 30949170, 2019). "The extent of tumor volume changes correlated with estimates of BRAF copies per cell." (PMID 31723142, 2019). "Poor DNA quality of the tumor sample did not allow us to assess the BRAF mutation status in the second patient." (PMID 31319569, 2019). "The patient’s tumor sample was found to be BRAF V600E mutated without other mutation (KRAS, EGFR [epidermal growth factor receptor], ALK, c-Kit)." (PMID 31340860, 2019). "In three of these discordant cases negative tissue results could be the result of sampling error in a tumor with intra-tumoral heterogeneity (among one or different tumor sites) of mutant BRAF expression." (PMID 31319569, 2019). "Another six patients had a BRAF or rare RAS mutation in ctDNA and/or tumor tissue." (PMID 31350822, 2019). "However, because BRAF mutant tumors are often right sided, the preplanned analysis to assess the impact of right-sided vs left-sided primary tumor location should provide an indirect assessment of BRAF mutation status." (PMID 30664496, 2019). "In non-terriers, neoplasms with BRAF mutation showed a significantly higher intensity of COX-2 expression than those without BRAF mutation (p ≤ 0.05)." (PMID 30893857, 2019). "Moreover, the clinical relevance of this finding is supported by investigation of the tumor material derived from a single patient treated with a combination of BRAF- and MEK-inhibitors resulting in undetectable levels of both ETS1 and TERT during therapy." (PMID 31391125, 2019). "The median CCF was significantly associated with BRAF-variant multiplicity, reflecting a shift in the overall allelic fraction of the tumor toward higher CCF values (non-neutral alleles)." (PMID 31723142, 2019). "In patients with treatment benefit (n = 21), no mutations in KRAS, NRAS, and BRAF were detected in tumor tissue." (PMID 31350822, 2019). "Indeed, other oncogenic mutations in the MAPK signaling pathway, such as mutations in NRAS, BRAF, or HER2 amplifications, have been identified in CRC and are implicated in tumor progression." (PMID 30858928, 2019).
tumor (continued). "Our results are of particular significance for patients who are negative for BRAF mutations, as we show that other mutations can be used for tumor monitoring." (PMID 30312528, 2019). "In gliomas, depending on the tumor histopathology and the patient’s clinical features, this integrated diagnosis may require assessing the tumor for IDH1 and IDH2 (IDH), H3F3A, and BRAF mutations, as well as the 1p/19q codeletion." (PMID 31167453, 2019). "Among 29 BRAF V600E-mutated cases, only one case (using a bronchial biopsy specimen) yielded a false negative result, which would be associated with inadequate tumor samples." (PMID 31234388, 2019). "Additionally, single-agent vemurafenib was shown to arrest cell proliferation and inhibit tumor growth in CRC cell lines and xenograft models expressing BRAF V600E mutation, respectively." (PMID 31661924, 2019). "If BRAF mutation cannot be detected, the tumor is either not caused by this mutation, no mutated cells are present in the specimen, or there is no TCC." (PMID 30893857, 2019). "Importantly, the MITF‐low/proliferative subtype, characterised by an absence of the expression of immune‐response genes, had only BRAF/NRAS‐mutated samples and more tumours with CDKN2A deletions, and was significantly associated with a poorer prognosis." (PMID 30511391, 2019). "We hypothesized that a population collapse around a single subclone may render a tumor more vulnerable to extinction when treated with BRAF-pathway inhibitors." (PMID 31723142, 2019). "Moreover, both WT and mutant BRAF proteins displayed perinuclear localization in tumor cell lines and tissues, adding another RAS pathway kinase to the list of those known to form PSCs." (PMID 31106232, 2019). "Mutations in BRAF or KRAS, that rarely coexist in CRC, constitutively activate the MAPK signaling pathway, which is involved in the regulation of several cellular processes, and inhibit the apoptosis mechanism, thus supporting tumor cell proliferation." (PMID 31330830, 2019). "BRAF V600E mutation status and ethnicity were related in the 2011–2012 data (P = 0.0187), as all black patients were wild-type for BRAF gene status, however within the OEG, BRAF mutations were only found in dMLH1 tumours (3/5; 60%)." (PMID 31636305, 2019). "There were characteristic signatures in the CCF density distributions that appeared to distinguish SKCM tumors with BRAF mutations from other tumor types; namely, the lack of low-frequency passenger variants." (PMID 31723142, 2019). "In addition, another BRAF inhibitor, vemurafenib, showed anti-tumor activity in BRAFV600E-positive PTCs refractory to radioactive iodine." (PMID 31810221, 2019). "The biomarker analyses of this study aimed to describe the biological impact of MEK-targeted inhibition of the MAPK pathway with binimetinib, establish the BRAF- and NRAS-mutated tumor genetic landscape, and explore the link between genetic pathway alterations and the response to binimetinib." (PMID 30956763, 2019). "Two patients did not have paired tumor tissue and plasma to determine the level of concordance of BRAF mutation and were excluded from the analyses (one tissue and one plasma BRAF mutational status unavailable)." (PMID 31319569, 2019). "They concluded that the HDAC inhibitor, vorinostat, might prolong the anti-tumor effects of BRAF/MEK inhibitor combination therapy." (PMID 31514399, 2019). "Furthermore, several studies have shown that CIMP positivity is associated with proximal colon location, presence of mucinous features, poor tumor differentiation, MSI, female gender and high BRAF mutation rates." (PMID 31324877, 2019). "The CIMP trait has been found to be associated with a variety of clinical, histopathological, and epidemiological characteristics, such as older age, female sex, proximal tumour location, poorly differentiated or mucinous histology, and high rates of MSI and BRAF mutation." (PMID 31690257, 2019).
tumor (continued). "Indeed, KRAS and NRAS mutant tumours and to a lesser extent BRAF mutant tumours are highly sensitive to combinations of PARP with MEK/ERK inhibitors in vitro, whereas for KRAS mutant models this evidence is available in vivo." (PMID 31374917, 2019). "Among the 502 submitted specimens, the only tumor carrying coexisting class-1 BRAF mutation and activating NRAS mutations was seen in a pleural effusion specimen taken 3 months after combined therapy with BRAF inhibitor and MEK inhibitor." (PMID 31277584, 2019). "However, the total PK activity of B-CPAP was higher than non-tumor cells and TPC1 cell line, indicating that the PK enzymatic reaction is dependent on BRAF mutations." (PMID 31423225, 2019). "In the first case, only 40–50% of tumor cells were positively stained with anti-BRAF V600E (VE1) antibody, the cells with positive staining showed the signal in cytoplasm and also strong signal in nuclei, the cytoplasmic staining was non-diffuse and non-uniform." (PMID 29127628, 2019). "A preclinical RAF inhibitor and sister compound to vemurafenib, PLX4720, successfully inhibits MEK and ERK phosphorylation, as well as downstream AKT phosphorylation, in BRAF V600E-mutated astrocytoma cell lines but not in wild-type tumor cell lines." (PMID 31466300, 2019). "Such heterogeneity could influence the nature and relative strength of the pathways through which each tumor responds or adapts to BRAF and MEK inhibition." (PMID 31581557, 2019). "Additionally, molecular tumor characteristics, such as microsatellite instability, CpG island methylator phenotype (CIMP), and mutations in KRAS and BRAF, were evaluated in our CRC study population." (PMID 30786938, 2019). "Previously, it was reported that tumor mechanisms of primary resistance include mutations in RAC1, loss of PTEN, and copy number increase of CCND1, while secondary resistance mechanisms include alternative expression of BRAF and PI3K." (PMID 30885146, 2019). "Also alterations in the tumor microenvironment seem to have a role in the development of resistance to BRAF/MEK inhibitors." (PMID 31762942, 2019). "For NSCLC, NGS-based tumor-profiling multiplex gene panels, such as Oncomine Dx target test or FoundationOne CDx, have recently been approved as companion diagnostics to detect mutations of EGFR and BRAF, or fusions of ALK and ROS1 in the US." (PMID 30943926, 2019). "Immunohistochemistry showed that the tumor cells were positive for BRAF V600E and pERK." (PMID 31345255, 2019). "Out of these 60 cases, 4 cases showed BRAF V600E stain intensity 1 in 25–90% of tumor cells." (PMID 29127628, 2019). "BRAF mutation determines an upregulation of the RAF-MAPK pathway, which leads to downstream activation of PTGS2 (COX-2) and to the increase of PGE2 production; this leads to higher survival and faster replication of tumor cells." (PMID 31661924, 2019). "For patients with mCRC, KRAS, NRAS and BRAF tumour genotyping has therefore a major impact on clinical management and genotyping results should be available within 7 working days to ensure a rational first-line treatment selection based on validated molecular data." (PMID 31265477, 2019). "Meanwhile, KRAS, NRAS and BRAF are potential tumor-driven genes themselves." (PMID 30416987, 2018). "While this combination is not considered immunotherapy, inhibitors of BRAF and associated pathways in the tumor cell have been shown to have immunomodulatory properties that contribute to their activity." (PMID 29848375, 2018). "The pyrosequencing analysis of tumor tissue showed that 10 out of 19 (52%) patients had a BRAF mutation, 5 out 19 (26%) harbored a NRAS mutation, and 4 out of 19 (21%) patients were WT for both BRAF and NRAS genes." (PMID 30546839, 2018).
tumor (continued). "A therapeutic combination of PI3K or FGFR inhibitors with BRAF/MEK inhibitors might therefore show enhanced anti-tumor effects." (PMID 30237393, 2018). "Combined inhibition of ALK and BRAF dramatically reduced tumour growth in vivo." (PMID 30290811, 2018). "This might pave the way for a persistant tumor cell population (“minimal residual disease”) which then may develop secondary mechanisms of resistance under continued BRAF inhibition." (PMID 30237393, 2018). "Notably, the treatment of these mice with a BRAF inhibitor (PLX4720) resulted in tumor regression followed by relapse, mimicking the human clinical condition." (PMID 29534457, 2018). "Cobimetinib is a highly specific selective, ATP-non-competitive inhibitor of MEK1/2 in neoplasias harboring BRAF V600E mutations." (PMID 29455659, 2018). "Gender, age, and tumor location distribution of cases used in KRAS and BRAF mutation analysis." (PMID 29879227, 2018). "Other significant somatic mutations were detected on Chromosome 16; BRAF gene (42% tumors), Chromosome 13; KDR (83% tumors) and Chromosome 20; STK11 with one missense variant detected in 8 of 12 (67%) samples in the matched normal and tumor pairs." (PMID 29854308, 2018). "Additionally, CIMP-high tumours with a BRAF mutation had a worse survival rate compared to CIMP-high with wild-type BRAF, which further implicates the BRAF mutation as a determining factor in detrimental patient outcome in microsatellite stable cancers." (PMID 30598662, 2018). "In patients with BRAF-mutant tumours, elevated serum CA 19-9 may identify a subgroup with highly aggressive disease and could contribute to improving therapeutic decisions." (PMID 29872151, 2018). "The mechanism of tumor progression robustly promoted by co-existing BRAF V600E and TERT promoter mutations is not known." (PMID 29422527, 2018). "Serum MMP-8 is associated with adverse CSS in CRC, independent of tumour stage, grade, lymphatic invasion, BRAF VE1 immunohistochemistry, MMR deficiency, Immunoscore and mGPS." (PMID 29808017, 2018). "The administration of the pembrolizumab molecule as first-line therapy to patients without genomic alterations in the genes EGFR, ALK, ROS1 and BRAF, and for whom 50 % of the tumor cells express PD-L1, has given back IHC a primordial role in the therapeutic care of patients with NSCLC." (PMID 29534030, 2018). "Interestingly, CK7 has been found in regions of tumour budding indicating progression of disease, which is also more prevalent in the aggressive BRAF mutant/MSS cancers." (PMID 30598662, 2018). "The ExBP‐RT method used for the BRAF V600E analyses detects mRNA of expressed mutations in tumor tissue, rather than the presence of mutated DNA." (PMID 29193645, 2018). "This classification divides CRC into four subtypes: MSI immune with MSI, BRAF mutated, and CIMP positive tumours; canonical with WNT and MYC activation; metabolic with KRAS mutated tumours; and mesenchymal, characterized by stromal infiltration and TGF-β activation." (PMID 30188916, 2018). "Also, high levels of LADH were detected, indicative of a highly proliferative tumor, supported by Ki-67+ PI and activation of MAPK pathway through BRAF mutation." (PMID 29774030, 2018). "Classes 2, 4, and 6 (no BRAF mutation) are also very well populated from cases of different histological tumor types (13%, 20%, 11%)." (PMID 30442178, 2018). "The most frequently mutated genes across all tumor types included KRAS (30 patients), PIK3CA (16 patients), BRAF (6 patients), EGFR (5 patients), NRAS (4 patients) and ERBB2 (3 patients) whereas CCND1, ERBB2, EGFR and MYC were the genes most frequently subjected to copy number gain." (PMID 29854313, 2018).